GIP (gastric inhibitory polypeptide)
Diseases named in the same sentence as GIP in open-access papers (continued):
Sharing a sentence is not in itself a finding about the gene and the disease.
diabetes (continued). "Interestingly, both GIP-GLP-1 co-agonists and GIP receptor antagonists administered in combination with GLP-1R agonists appear to be efficient with respect to both weight loss and control of diabetes, although the molecular mechanisms behind these effects remain unknown." (PMID 33339298, 2020). "GIP concentrations were successfully measured during OGTTs in two independent populations (Malmö Diet Cancer–Cardiovascular Cohort [MDC-CC] and Prevalence, Prediction and Prevention of Diabetes in Botnia [PPP-Botnia]) in a total of 8044 subjects." (PMID 31974732, 2020). "In diabetes, pancreatic β‐cells were still able to respond to GLP‐1, making GLP‐1 an attractive therapeutic for diabetes and leaving GIP to become known as the “forgotten incretin.”13 However GIP, not GLP‐1, has a direct effect on bone." (PMID 31687648, 2019). "Data indicate that the incretin (gastric hormone) known as glucose‐dependent insulinotropic polypeptide (GIP) that is anabolic to osteoblasts strongly upregulates LOX, and that this regulation is disrupted in the streptozotocin‐induced model of diabetes in mice." (PMID 31687648, 2019). "In a cross-sectional study, GIP secretion in early phase was found to be positively correlated with body mass index (BMI) in non-obese and obese patients with type 2 diabetes mellitus." (PMID 31477157, 2019). "Twenty patients of active acromegaly (10 each, with and without diabetes) underwent hyperinsulinemic euglycaemic clamp and mixed meal test, before and after surgery, to measure indices of IS, β-cell function, GIP, GLP-1 and glucagon response." (PMID 30948746, 2019). "To confirm that decreased GIP signaling is specifically due to dopamine and not some other signaling dysregulation in diabetes, we rescued GIP signaling and LOX production in diabetic osteoblasts by inhibiting dopamine receptor activity." (PMID 31687648, 2019). "The present study aimed to examine and compare the effects of SMART WASHOKU and modern Japanese meals on VFA and GIP secretions in overweight/obese men without diabetes." (PMID 31477157, 2019). "The AUC for GIP was modestly higher in patients of acromegaly with diabetes than in those without diabetes." (PMID 30948746, 2019). "No other associations were observed between inflammation-related markers and insulin, GIP, or PP among people who did not report a history of diabetes." (PMID 28753646, 2017). "The objectives of this study were to determine the effects of exogenous GIP infusion on blood glucose concentrations, glucose absorption, insulinaemia and gastric emptying in critically ill patients without known diabetes." (PMID 25613747, 2015). "Since GLP-1 and GIP are rapidly degraded and inactivated by dipeptidyl peptidase-4 (DPP-4), inhibition of DPP-4 and/or DPP-4-resistant GLP-1 analogues have been proposed as a potential target for the treatment of diabetes." (PMID 25582643, 2015). "The in vitro suppressive effect of GIP on foam cell formation was blunted in macrophages from diabetic mice vs. nondiabetic mice (15% vs. 35%), probably because of the reduced GIPR in the macrophages in diabetes." (PMID 22536426, 2012). "However, for attempts to treat diabetes in humans with CCK receptor agonists, for safety reasons, it has to be low doses of the agonist in combination with analogues of the major incretins such as GLP‐1 and GIP." (PMID 40557463, 2025). "One such class of medications that has shown considerable promise in treating diabetes is incretin-based pharmacotherapies, including glucagon-like peptide-1 receptor agonists, or GLP-1 RAs, plus or minus glucose-dependent insulinotropic polypeptide receptor agonists (GLP-1/GIP RAs)." (PMID 40881557, 2025). "However, GIP was not successfully used for diabetes treatment, whereas Glucagon‐like peptide 1 (GLP‐1), the other incretin that was later characterized, was in line with a drug for diabetes, so‐called a GLP‐1 receptor agonist." (PMID 39540705, 2025).
diabetes (continued). "Therefore, potential beneficial effects of both GIP and GLP-1 have been highlighted and might represent a suitable therapeutical option in the treatment of diabetes-induced bone fragility." (PMID 39770498, 2024). "Incretin action of GIP is dramatically reduced in the presence of diabetes, as demonstrated by the evidence that glucose-dependent insulin secretion is not potentiated by GIP administration in subjects with diabetes." (PMID 38831203, 2024). "There are also other novel targets for diabetes mellitus control that could be exploited, such as GPCR 119, GPER, 11β-hydroxysteroid dehydrogenase 1, Vaspin, Metrnl, PEDF, Fetuin-A, ACRP 30(AdipoQ), Visfatin, Melatonin, GIP, GPCR." (PMID 36782201, 2023). "In a subset of mice from the current study (WT and AD groups with the sham surgery), we previously reported that 3xTg-AD females did not display increased plasma levels of other diabetes markers (e.g., insulin, GIP, GLP-1, PAI-1, resistin) or peripheral inflammation." (PMID 35568928, 2022). "GIP, an incretin, has not been used due to lack of promising action against diabetes." (PMID 35949358, 2022). "The findings do not extend to effects of other glucose-lowering medications that indirectly alter GIP signalling, and may not be applicable to individuals with diabetes, in whom the physiological effects of GIP signalling may be altered." (PMID 34505161, 2021). "However, patients of acromegaly with diabetes had a significantly lower C-peptide/GIP ratio as compared to those without diabetes despite having markedly increased GIP levels and moderately preserved β-cell function suggesting GIP resistance." (PMID 30948746, 2019). "The rise in GIP levels was not seen in the SD- αMG group, suggesting that the ‘porto-incretin reflex’ is upregulated in diabetes and may reflect a pathophysiological regulatory mechanism." (PMID 27806092, 2016). "Despite that lacking secretion or faster clearance of incretin are not pathogenic factors in diabetes, GLP-1 has become a molecular target for therapeutics of type 2 diabetes mellitus (type 2 DM) since its insulinotropic activity is still active in these patients, but not GIP." (PMID 23589719, 2013). "GIP stimulates also glucose-dependent insulin release in people without diabetes and may have a role in appetite regulation: despite mixed findings, preclinical research suggests that the addition of GIP RA may enhance appetite suppression and WL associated with a fixed-dose of GLP-1 RA." (PMID 40741227, 2025). "An important observation was made in a study where GIP infusion was described to significantly increase hyperglycemia and body weight in ApoE−/− mice with STZ-induced diabetes, but not in spontaneously diabetic db/db mice, suggesting that GIP might actually modulate the effects of STZ." (PMID 25785279, 2015). "Factors associated with angiogenesis or diabetes did not exhibit statistically significant differences, with the exception of two incretins, GLP-1, which was significantly higher in the complication free group (without POPF), and GIP, which had increased levels in the tissues with POPF." (PMID 25120588, 2014). "The more recently developed tirzepatide is a member of the class known as “twincretins,” with GIP RA activity potentiating the effects of the GLP RA and resulting in comparable, if not better, control of diabetes and weight." (PMID 41001580, 2025). "Individuals with diabetes had significantly higher levels of Gal-4, higher prevalence of IHD, higher BMI, higher levels of GIP, triglycerides, cystatin c, and FPG, along with higher HOMA-IR, compared to individuals without diabetes." (PMID 37985679, 2023). "Our aim was to assess the GLP‐1 and GIP responses to carbohydrate and protein/fat meals in adults with KCNJ11‐PNDM, and to compare these with adults without diabetes." (PMID 37602910, 2023).
diabetes (continued). "Insulin secretion increased during co-infusion, compared with GIP alone or GLP-2 alone, but not with GLP-1 alone; this result highlighted the lack of GIP stimulus on insulin release in patients with diabetes." (PMID 35054422, 2021). "IHC positivity for GIP, but not GLP-1, staining cells in duodenum and colon was significantly lower in acromegalics with diabetes as compared to healthy controls possibly because of high K-cell turnover." (PMID 30948746, 2019). "In the diabetes panel, in addition to IL-6, the GLP-1 concentration was found to be higher in patients without a fistula, whereas the GIP level was observed at significantly higher concentrations in the fistula group." (PMID 25120588, 2014). "GIP secretion was stimulated by glucose and the non-metabolisable SGLT1 substrate α-MDG, and glucose-triggered GIP release was inhibited by sotagliflozin, an SGLT1/2 blocker used for management of diabetes and chronic kidney disease." (PMID 39441374, 2025). "CCK peptides have evoked some interest in diabetes research, not least because CCK, in itself being a minor incretin, may potentiate the effect of major incretins such as GLP‐1 and GIP." (PMID 40557463, 2025). "Unlike those with diabetes, obese individuals maintain both, GLP-1 and GIP responses." (PMID 41471111, 2025). "With the development of the first GIP/GLP-1 co-agonist, tirzepatide, there has been an exponential increase in the effectiveness of incretin-mimetic pharmacological therapy for weight control in obese patients with and without diabetes." (PMID 38831203, 2024).
Insulin resistance (115 papers, 2009 to 2026). Increased resistance towards insulin, that is, diminished effectiveness of insulin in reducing blood glucose levels. "GIP agonists have been found to alleviate symptoms that are a result of neurodegenerative diseases that exhibit significant insulin resistance, like AD, by reducing the amount of neuronal plaque caused by neuroinflammation." (PMID 39857716, 2025). "Ineffective or low amounts of GLP-1 and extremely high levels of GIP cause the function of β cells to decrease, while also causing insulin resistance to increase." (PMID 39857716, 2025). "K cell hyperplasia‐associated GIP hypersecretion promotes the build up of fat and insulin resistance in aged mice, which was ameliorated by ablation of the GIP receptor or GIP itself in aged mice." (PMID 36000805, 2022). "GIP (R = −0.01, p-value = 0.87) and C-peptide (R = −0.54, p-value <0.001) markers associated with insulin resistance were significantly elevated in men." (PMID 31941993, 2020). "High fasting levels of TG, which is a common component of insulin resistance, are significantly associated with GIP (r = −0.43, n = 18, p = 0.05) and MTRNR2L1 (r = 0.65, n = 18, p < 0.01) but only tend to be associated with MSMB (r = −0.40, n = 18, p = 0.08)." (PMID 26376914, 2015). "Daily administration of GIP antagonists, such as (Pro3)GIP, has been able to promote weight loss and ameliorate insulin resistance in mice." (PMID 19254363, 2009). "Furthermore, it enhances glucose-dependent insulinotropic polypeptide (GIP) secretion and improves insulin sensitivity, counteracting hyperuricemia caused by insulin resistance." (PMID 41031353, 2025). "Additionally, GIP is implicated in increasing cytokine penetration into adipocytes to drive insulin-resistance within these peripheral tissues." (PMID 38861364, 2024). "Given the substantial role of adiposity in the development of glycaemic dysfunction and insulin resistance, we performed mediation analyses to explore whether the causal effect of GIP and IL-1RA may be partially mediated through BMI." (PMID 38049854, 2023). "Several GWAS have identified variants positioned in the GIPR locus, including the E354Q GIPR variant, to associate with increased 2-h glucose levels, decreased insulin secretion, insulin resistance and risk of T2D, further supporting the importance of the GIP-GIPR axis in glucose regulation." (PMID 34760890, 2021). "GIP is associated with insulin resistance, as its levels increase, as shown by our results, and therefore the increase in insulin secretion may also be, at least in part, secondary to increases in insulin resistance." (PMID 40214973, 2025). "This study shows that long-term WR after RYGB is associated with elevated fasting glucose, insulin resistance, and a blunted postprandial GLP-1 response alongside an exaggerated GIP response." (PMID 40687579, 2025). "Dipeptidyl peptidase-4 (DPP4) is a multifunctional protein with peptidase activity on substrates like GLP-1 and GIP, being involved in hyperglycemia, insulin resistance, dyslipidemia, oxidative stress, and inflammation." (PMID 40431452, 2025). "The wild-type mice developed GIP hypersecretion, extreme visceral and subcutaneous fat deposition, and insulin resistance." (PMID 40214973, 2025). "This is thought to represent indirect effects (mediated by reductions in insulin resistance) and possible direct effects (via surgically induced changes in GIP, GLP-1, and affiliated peptide hormones) on the ovaries and the hypothalamic–pituitary–adrenal axis." (PMID 39857716, 2025). "The ovariectomized wild-type mice gained weight with increased fat mass and insulin resistance as expected, through effects of reduced oestrogen on the regulation of body weight, mediated in part by GIP signaling." (PMID 40431453, 2025).
Insulin resistance (continued). "This process is very important for patients with T2DM, as this allows for GIP levels to decrease, which will lower insulin resistance and blood glucose levels, increase the productivity of GLP-1, improve β cell function, and even decrease body weight." (PMID 39857716, 2025). "Future studies are needed to dissect the associations (if any) between changes in body fat distribution and insulin resistance on perturbed GIP secretion." (PMID 38087928, 2024). "Some effects of GIP differ from those of GLP-1: under conditions of insulin resistance (IR), it promotes lipid deposition in mice subcutaneous fat cells; it does not affect gastric emptying; and its effect on blood glucose is impaired in chronic hyperglycemia." (PMID 38255264, 2024). "Increased GIP signaling plays an important role in adipose tissue inflammation and insulin resistance in obese mice." (PMID 37442561, 2023). "Bioactive peptides also induce the release of incretin hormones including glucagon‐like peptide‐1 (GLP‐1) and glucose-dependent insulinotropic polypeptide (GIP) that play a significant role in the enhancement of insulin resistance." (PMID 37798798, 2023). "Wild-type mice fed a high-fat diet showed high secretion of GIP and extreme visceral and subcutaneous fat deposition and insulin resistance." (PMID 35647086, 2022). "After 20 weeks of SuperJump activity GLP-1 and GIP levels were significantly increased while fasting insulin, glucose, insulin resistance, were significantly reduced." (PMID 35205162, 2022). "Through high-fat and high-sugar diet (HSHFD)-induced T2DM model KKAy mice, we explored the effect of RB on body weight, blood glucose, glucose tolerance, insulin tolerance, insulin resistance index, glucolipid metabolism, and serum GIP and GLP-1 in T2DM mice." (PMID 35571083, 2022). "In this study, GIP is shown to be involved in age-related obesity and insulin resistance under normal fat diet feeding condition." (PMID 31977316, 2020). "High GIP group was characterized by elevated fasting glucose, with impaired fasting glucose (5.6–6.9 mmol/L) in half of the cases, and enhanced insulin resistance HOMA-IR (Q2 (Q3–Q1): 3.68 (2.72–5.42) versus 2.70 (2.13–4.33), p = 0.021)." (PMID 32069846, 2020). "In conclusion, GIP is involved in age-related obesity and insulin resistance, and inhibition of GIP secretion alleviates age-related body weight and fat mass gain, and insulin resistance under carbohydrate-based feeding condition." (PMID 31977316, 2020). "In accord with this, our present data suggest that leptin replenishment by fat transplantation to Lepob/ob mice ameliorated hypersecretion of GIP, as well as insulin resistance." (PMID 31509948, 2019). "There is also evidence that GIP induces both in mice and human fat cells expression and release of inflammatory cytokines with possible relapse on insulin resistance." (PMID 31412576, 2019). "Luteolin improved insulin resistance by normalizing pancreatic islet dysfunction and differentially modulating the plasma glucagon-like peptide-1 and gastric inhibitory polypeptide levels." (PMID 30282902, 2018). "The IIDSG excludes the duodenum, leading to attenuated release of Rubino’s factor (anti-incretin factor, which promotes insulin resistance) and Gastric Inhibitory Polypeptide (GIP)." (PMID 25426451, 2014). "Recently, GIP was proposed as having a role in inflammation and insulin resistance by modulating the expression of osteopontin in adipose tissue." (PMID 24086540, 2013). "In periods with continuously elevated energy intake excess GIP secretion may lead to inflammatory processes, ectopic lipid storage (liver fat, visceral fat), and insulin resistance." (PMID 40076626, 2025). "This is attributed to compromised effects of native GIP on adipose tissue resulting in clearance of triglyceride from adipose and liver stores, thereby substantially improving insulin sensitivity and alleviating insulin resistance." (PMID 40024571, 2025).